INTS5 (integrator complex subunit 5)
Description:
Component of the integrator complex, a multiprotein complex that terminates RNA polymerase II (Pol II) transcription in the promoter-proximal region of genes. The integrator complex provides a quality checkpoint during transcription elongation by driving premature transcription termination of transcripts that are unfavorably configured for transcriptional elongation: the complex terminates transcription by (1) catalyzing dephosphorylation of the C-terminal domain (CTD) of Pol II subunit POLR2A/RPB1 and SUPT5H/SPT5, (2) degrading the exiting nascent RNA transcript via endonuclease activity and (3) promoting the release of Pol II from bound DNA. The integrator complex is also involved in terminating the synthesis of non-coding Pol II transcripts, such as enhancer RNAs (eRNAs), small nuclear RNAs (snRNAs), telomerase RNAs and long non-coding RNAs (lncRNAs). Mediates recruitment of cytoplasmic dynein to the nuclear envelope, probably as component of the integrator complex.
Synonyms: Int5; KIAA1698
Tractability: Antibody: UniProt predicts a signal peptide or a membrane-spanning region. PROTAC: ubiquitination databases record sites on it; its protein half-life has been measured.
Gene: Protein-coding gene on chromosome 11 (62,646,848 to 62,653,302, reverse strand). Ensembl gene ENSG00000185085.
Subcellular location: Nucleus; Cytoplasm; Nucleus membrane
Subcellular location (Human Protein Atlas): Nucleoplasm; Cytosol
Pathways (Reactome):
Gene expression (Transcription): RNA polymerase II transcribes snRNA genes
Gene Ontology:
Molecular function: protein binding
Biological process: regulation of transcription elongation by RNA polymerase II; RNA polymerase II transcription initiation surveillance; snRNA processing; snRNA 3'-end processing
Cellular component: cytoplasm; cytosol; INTAC complex; integrator complex; membrane; nucleoplasm; nucleus; nuclear membrane
Genetic constraint (gnomAD): Loss-of-function variants: 29 observed, 62.17 expected, observed/expected ratio (o/e) 0.47, 90% interval 0.35 to 0.64. The upper end of that interval is the gene's LOEUF score, 0.64, which puts it in group 2 of 6, group 1 being the genes least tolerant of losing a copy. Missense variants: 1,129 observed, 1,371.7 expected, observed/expected ratio (o/e) 0.82, 90% interval 0.78 to 0.87. Synonymous variants: 588 observed, 588.92 expected, observed/expected ratio (o/e) 1, 90% interval 0.93 to 1.07.
Homologues: Orthologues: chimpanzee INTS5 (99% identical), macaque INTS5 (99% identical), rabbit INTS5 (98% identical), dog INTS5 (98% identical), pig INTS5 (97% identical), mouse Ints5 (95% identical), rat Ints5 (93% identical), guinea pig INTS5 (92% identical), zebrafish ints5 (51% identical), Drosophila melanogaster omd (23% identical), Caenorhabditis elegans ints-5 (17% identical).
Diseases named in the same sentence as INTS5 in open-access papers:
INTS5 is named in the same sentence as 1 disease in open-access papers, as found by Europe PMC text mining. Sharing a sentence is not in itself a finding about the gene and the disease.
INTS5 shares sentences with these, for which no sentence is quoted: tumor (1 paper).